TNF (tumor necrosis factor)
Diseases named in the same sentence as TNF in open-access papers (continued):
Sharing a sentence is not in itself a finding about the gene and the disease.
infection (continued). "Unexpectedly, 6 days following infection with the ΔhtrA gene mutant but not the WT strain, IFN-γ, TNF-α, and NO levels were up-regulated in splenic ex vivo biopsies (p < 0.05−0.0005)." (PMID 24959425, 2014). "As the downstream targets of NF‐κB activation, we found that inflammatory cytokines IL‐2, IL‐4, IL‐6, TNF‐α, and IFN‐γ were significantly increased in the infected organoids compared to the organoids without any infection." (PMID 25214524, 2014). "After infection, CD1c+ DCs expressed HLA-DR, CD40, and CD83 (top) and produced IL-6, TNF-α, and IL-1β but not IL-23, TGF-β, or IL-12p70 (F and data not shown)." (PMID 25071784, 2014). "It is worth noting that J774A.1 cells post-infection treated with LieIF/IFN-γ did not have elevated expression levels of MIP-1α and TNF-α mRNA." (PMID 24830439, 2014). "However, we did not detect an upregulation of IFN-γ or TNF-α expression by transcriptome analysis in vivo, suggesting that these cytokines might not contribute significantly towards intestinal epithelial changes during early infection." (PMID 25166758, 2014). "Four hours post-infection inflammation is increased in the peritoneum and 66% of wt MC58 show TNF-α uptake compared with no uptake in the ΔpglC/L mutant." (PMID 24107297, 2013). "The responses of BDCA1+ mDCs from different donors varied upon EV1 infection, with part (∼60%) of the donors inducing high levels of IL-6 and TNF-α, whereas the other donors responded poorly or produced no pro-inflammatory cytokines at all upon EV1 infection." (PMID 23638101, 2013). "Unlike early TNFα synthesis that requires IFN-I after both i.p. and i.g. infection, the production of IL6 and MCP1 during the initial 24 h of infection is reduced specifically when bacteria enter their host via the intestine." (PMID 23840314, 2013). "IL-6 has also the highest sensitivity (89%) and negative predictive value (91%) at the onset of infection compared with other biochemical markers, including CRP, TNF, and E-selectin." (PMID 24570828, 2013). "Yeast (Candida albicans) and bacterial (Gram negative and positive organisms and their products) infections act as agonists for TLR2/4/5 in vaginal and skin explants and also induce TNFα production." (PMID 24278768, 2013). "Efficient and comparable inhibition of TNF-α release was observed after infection with LVS and ΔpdpC, but not after infection with the control strain ΔiglA." (PMID 23356941, 2013). "In contrast, TNFα, CD80 and A3Z1 and IL-10 expression did not increase upon infection with most of the strains." (PMID 24070317, 2013). "Unlike that observed with BALB/c WT mice, infection of BALB/c STAT6 −/− mice with VV-HA-IL-4 compared to VV-HA control did not impair the IFN-γ and TNF-α cytokine production capacity of KdA5275–83 or KdF226–34 specific-CD8+ T cells." (PMID 23383283, 2013). "In contrast to TNF-α we found IL-6 neither to induce apoptosis in the concentration range used, nor to enhance PICD after infection with E. coli." (PMID 23349721, 2013). "Expression of TNFα, IL1b, IFNγ, TGFβ and IL10 was still significantly upregulated in the infected animals compared to the non-infected 7 days after infection." (PMID 22815907, 2012). "However, it is also noteworthy that the immune-modulatory cytokine IL10 is induced upon infection by MCMV in MΦs and in vivo and since IL10 is known to function as an anti-inflammatory mediator, it is possible that a host IL10 autocrine loop might be involved in modulating TNFα." (PMID 22952450, 2012). "We observed that infection of pDCs with ΔE3L vaccinia virus fails to induce IFN-α and TNF secretion, however, implying that additional inhibitors are produced by the ΔE3L vaccinia virus in human pDCs." (PMID 22606294, 2012). "Some of the most remarkable characteristics observed at early times after infection by DENV are the lack of IFNα/β induction and a robust induction of pro-inflammatory cytokines like TNFα." (PMID 23055924, 2012).
infection (continued). "The lack of significant TNF-α expression has ramifications on the function and production of IFN-γ against active infection, which has been documented previously." (PMID 22558103, 2012). "We observed that infection with ΔA46R, ΔA52R or ΔA46R ΔA52R alone did not induce the production of IFN-α or TNF (data not shown)." (PMID 22606294, 2012). "We found that in pig macrophages the levels of FasL and TNF-α remained undetectable, while TNF-related apoptosis-inducing ligand (TRAIL) seemed to be most abundant before infection, based on Ct values from realtime RT-PCR (data not shown)." (PMID 22279582, 2012). "In vivo we observed a relatively enhanced production of the pro-inflammatory cytokines TNFα and IFNß but not for the anti-inflammatory cytokine, IL10, with MCMVdie1 infection." (PMID 22952450, 2012). "Infection of human pDCs with each of the four E3 mutants alone failed to induce IFN-α and TNF secretion (data not shown)." (PMID 22606294, 2012). "Moreover, the finding that TNF could stimulate the production of MCP-1 by AEC to a similar extent as LPS is of particular interest because MCP-1 plays a role in the recruitment of monocytes and macrophages to sites of injury and infection and macrophages are the main producers of TNF." (PMID 22393384, 2012). "Depletion of γδ T cells did not appear to affect TNF-α production by splenocytes from B. abortus-infected mice at 4 or 7 days post-infection, and stimulation of splenocytes with plate-bound anti- γδ TCR mAb did not enhance TNF-α production (data not shown)." (PMID 21765931, 2011). "We have confirmed increase of TNFα protein expression by alternate methods including ELISA and Reverse Phase protein MicroArray (RPMA) following MP12 infection of human cells (data not shown)." (PMID 21655261, 2011). "The “pro-migratory” 7.13 strain induced a significantly higher increase in TNFα secretion compared to the “non-migratory” 26695 strain, suggesting a role for this cytokine in MSC migration induced by infection with the 7.13 strain." (PMID 22216156, 2011). "In the MDDC alone supernatant only low amounts of TNF-α, IL-6, MIP-1α and MIP-1β were found after MVA and MVA-B infection (data not shown)." (PMID 21625608, 2011). "Infection of both monocytes and macrophages with TCRV also resulted in the release of high levels of IL-6, IL-10 and TNF-α, while levels of IFN-α, IFN-β and IL-12 were not affected." (PMID 21572983, 2011). "Infection with wild type UPEC CFT073 and 536 as well all five PAI deletion mutants failed to induce IL-6 or TNF-α secretion and even suppressed the production of IL-6 below basal levels." (PMID 22164293, 2011). "Infection of MM with HPAIV H5N1 also results in an excessive immune response, marked by the high induction of the pro-inflammatory cytokine TNF-alpha, which is not observed after infection with seasonal H1N1 or H3N2 virus." (PMID 21731493, 2011). "Infection with Tn:Rv0431 resulted in greater expression of transcripts for IL-12p40, IL-6, Delta4, CD40, GM-CSF, RANTES, TNFα and MCP-1, but not GITRL or iNOS, than WT Mtb, both with (not shown) or without IFNγ costimulation." (PMID 21170273, 2010). "For discrimination of mild infection, the use of SOD-1 improves the correct case detection by more than 45% compared with the use of TNF-alpha, in addition to being a better identifier of negative cases." (PMID 20386593, 2010). "Plasma cytokine levels were either not different between the groups (TNF-α, IL-6, IFN-γ) or below detection (MCP-1, IL-12, IL-10) at both 24 and 48 hours after infection (data not shown)." (PMID 20682036, 2010). "This showed that P. yoelii 265BY infection in B6 mice is characterized by a peak of IFN-γ in the serum at day 5 p.i., while concentrations of circulating TNF and IL-12 stayed at the levels found in non-infected animals." (PMID 19508725, 2009).
infection (continued). "Upon infection, latent cells are defined as those that do not express constitutively GFP, but need further stimuli of HIV promoter by mitogens (PMA) or cytokines (TNF-α)." (PMID 19148280, 2009). "Unlike IL-17 and TNF-α gene expression, the IFN-γ response returned to control levels by day 14 post-infection, suggesting that a Th1 response is induced only at the peak of infection and is more transient than the Th17 response." (PMID 19759900, 2009). "In three of the four BCG+ individuals without infection, IFN-γ and TNF-α production were mainly detected only after PPD stimulation." (PMID 17655752, 2007). "Notably, at early stages of infection (14 d p.i.), there was no significant production of IL-17 and TNF-α by spleen- or heart-derived T cells from infected B2R−/− mice, whether detected by conventional recall assays or polyclonal activation with anti-CD3 antibodies (unpublished data)." (PMID 18052532, 2007). "While p65 was detected in the nucleus of control and TNF-α-treated cells, almost no signal for p65 was found after RML6 infection." (PMID 17573907, 2007). "In keeping with inflammatory cell numbers, weanling mice did not have elevated TNFα, IFNγ, MCP-1 or IL-6 in BALF at any timepoint, although VEGF was elevated at 7 d post infection." (PMID 16324223, 2005). "The cytokine profile measured in BALF from adult and weanling mice mirrored the inflammatory profile, with adult mice showing increased levels of TNFα, IFNγ, MCP-1, IL-6 and VEGF at 7 d post infection but not at 5 d (not measured at 10 d)." (PMID 16324223, 2005). "Therefore, lack of soluble TNF may allow slow growth of mycobacteria during the chronic infection, with likely progressive hypoxemia due to chronic pneumonia, leading to death in the chronic phase of infection." (PMID 16285886, 2005). "In the presence of AAV-siRNA infection, the production of IFN-γ, TNF-α, IL-8, IL-6, and IL-12 did not change significantly compared with cultured DCs." (PMID 15301687, 2004). "Moreover, in the absence of NTHi infection, neither TLR2 nor TLR4 inhibitors had an effect on TNFα expression in MDMs." (PMID 40013145, 2025). "When we examined the expression levels of inflammatory cytokines and interferons, we found that the expression levels of interleukin-1 beta (IL-1β), interleukin-6 (IL-6), tumor necrosis factor (TNF-α), interferon beta (IFN-β), and interferon lambda-1 (IFN-λ1) were not altered by MPXV infection." (PMID 41542170, 2025). "TNF-α levels differed between groups prior to vaccination and after infection challenge, and IL-8 and MCP-1 were elevated at isolated time points in vaccinated animals post-infection, though these changes were not sustained." (PMID 41159782, 2025). "However, serum levels of TNF-α, IL-6, and IFN-γ were significantly higher in the infection group than in the non-infection group, with statistically significant differences (P<0.05)." (PMID 40677522, 2025). "We measured Type 1 (IFN-γ, TNF-α, IL-2), Type 17 (IL-17, IL-22), and proinflammatory cytokines (IL-1α, IL-1β) in QuantiFERON (QFT) supernatants from TBI individuals with (TBI+Hel+) and without (TBI+Hel−) infection." (PMID 41583474, 2025). "This persistent, subclinical inflammation, termed “inflammaging”, is characterized by modest but sustained elevations of circulating cytokines such as interleukin-6 (IL-6), tumor necrosis factor alpha (TNF-α), and C-reactive protein (CRP), even in the absence of infection." (PMID 41373468, 2025). "This infection did not result in significant changes in TEER compared to mock at any time point for either virus, whilst addition of TNF-α, as a positive control, led to clear disruption of barrier function to a mean of 64% of the mock-infected control at 72 hpi." (PMID 40295794, 2024). "Interestingly, the stimulation with TNF-α + IFN-γ of CI2-infected BMMΦ was highly effective in the elimination of the parasites and not effective in the case of infection with the QRO isolate." (PMID 39452749, 2024).
infection (continued). "Finally, there was a group of cytokines and chemokines: TNF, IFNγ, CCL5, CXCL9, CXCL10 and CXCL13, which were early after infection elevated in the vaccinated but not detectable in the naive animals, suggesting an adaptive immune response as the trigger." (PMID 39472590, 2024). "This study utilized human cervical tissue explants as an infection model to demonstrate that GC inoculation increases the secretion levels of both the proinflammatory cytokines IL-1β and TNF-α and the antiinflammatory cytokines IL-10 but not TGF-β and IL-17A during the first 24 hours of infection." (PMID 39585777, 2024). "Cytokines known as inappetence-inducing factors including IL-6, IL-1β, TNF, and IFN-g were not significantly different in the brain after infection, whereas IL-1α was significantly reduced (P < 0.0001) in the brain of both αCD8α treated and aIL-1a treated mice compared to RSV treated." (PMID 38382577, 2024). "Cytokine signaling of IL-1β, IL-23, IL-17A, CCL7, CXCL10, TRAIL, CD40L, and BAFF provides protection against acute WNV infection in mice; IL-10 and IL-22 aid in WNV pathogenicity; IL-6 and IL-12 had no apparent effect during infection; and CCL2, TNF-α, and FasL roles remain elusive." (PMID 36992514, 2023). "Together these data suggest that IFNγ and TNFα but not perforin are required for control of CCHFV during the acute disease, while TNFα and perforin may impair clearance of the infection at later timepoints." (PMID 37866114, 2023). "Thus, our data demonstrate that P1 mRNA has the capability to activate both CD4+ and CD8+ T cells in participants, irrespective of their past infection status, resulting in a preferential production of IFN-γ and TNF-α." (PMID 38051989, 2023). "The infection of MDMs with Mtb opsonized with hSAA-1, compared to the infection with nonopsonized bacilli, led to at least a 2-fold increase in the concentrations of CSF2, CSF3, IL-1α, IL-1β, IL-6, IL-12, CCL15, and TNF-α with the most potent 10-fold increase observed for CCL5." (PMID 37781389, 2023). "Infection with the H7N7 resulted in increased levels of CCL2, IFNγ, IL1β, IL-6, and TNFα in the brains of mice, whether or not they had been previously vaccinated." (PMID 37063291, 2023). "Additionally, infection with HN878 and rpoB-S450L Mtb also resulted in increased TNF production, while rpoB-H445Y infection did not." (PMID 37682004, 2023). "The levels of proinflammatory cytokines (IP-10, IL-1β, IL-6, IL-8, TNF-α and GM-CSF) and anti-virus-related factors (IFN-α, IFN-λ1 and IFN-γ) were upregulated in the blood samples of the six patients as compared those of the control patients without infection." (PMID 37090924, 2023). "TNF has been described for its essential role in promoting the survival of CD169+ macrophages during the infection of VSV in mice, suggesting that the ability of both viruses to induce TNF expression in macrophages was not responsible for the phenotypic differences seen in both viruses in pigs." (PMID 37513744, 2023). "Together, these observations suggest that the combined effect of TNF-α reduction and cAMP accumulation enables the host cells to control SARS-CoV-2 replication and infection effectively, without triggering inflammation, which would contribute to exacerbated host cell death and disease pathology." (PMID 37854602, 2023). "We found that after infection, cells from patients with AUD had a significant decrease in transepithelial resistance (TER) and showed enhanced secretion of several proinflammatory cytokines including TNFα, IL-1β, and IFNγ as compared with non-AUD cells." (PMID 37786945, 2023). "Moreover, 60% to 90% of CD4+ or CD8+ EM T lymphocytes produced IL-10 and/or TGF-β1, with up to 40% of the cells producing TNF-α and IFN-γ, and no clear indication of immunological function after infection." (PMID 35720410, 2022).
infection (continued). "While supplementation may seem counterintuitive, partial restoration of TNF-α and IFN-γ may allow for infection clearance without amplifying the immune response enough to cause sequelae." (PMID 36159650, 2022). "TNF-α plus cycloheximide (CHX) treatment triggered autocleavage of caspase-8 as well as its cleavages of Bid, caspase-3, caspase-7, and PARP1, all of which was blocked by infection with CopC-positive C. violaceum but not ΔcopC strain." (PMID 35446120, 2022). "In our research, the mRNA expression of FADD and TNF-α which belong to extrinsic pathway were not significantly altered after NNV infection, indicating that it was the intrinsic pathway that was activated in CAB cells post-infection." (PMID 36298739, 2022). "This study reveals that the healing efficacy of G. mangostana crude extract was achieved by reducing the expression of antioxidant genes (CAT, SOD, and GPx) and inflammatory cytokine genes (TGF-β, TNF-α, IFN-γ, and IL-10) to levels similar to those of the no infection group." (PMID 35369604, 2022). "Instead, infection with the virulent 22653/14 ASFV did not alter any surface marker expression and did not trigger the release of either IFNβ, anti-inflammatory IL-10, proinflammatory (IL-1β, IL-6, IL-8, TNF-α), and pro-Th1 (IL-12, IL-18) cytokines." (PMID 35215216, 2022). "Therefore, we monitored the levels of IL-6, IFN-γ, IL-2, IL-10, TGF-β, TNF-α, IL-12, and IL-17 in the lung lysates of M. tb-infected mice with and without L-GSH treatment at varying stages of the infection to assess the granulomatous response." (PMID 35453358, 2022). "However, TNF-alpha values showed no decisive results, leading to the conclusion that CRP values in this study are not triggered by infection." (PMID 36430283, 2022). "falciparum-specific IL-10 producing CD4+ T cells but not with IFNγ or TNFα producing CD4+ cells; however, these cells could not prevent infection prospectively." (PMID 34414129, 2021). "As with infection with THP-1 macrophages, NuLi-1 cells infected with chronic P. aeruginosa isolates induced less IL-1β expression but more IL-6 expression, while the expression of TNF and IL-10 were undetectable (data not shown)." (PMID 33664232, 2021). "aureus human antibody responses in huNSG serum using our custom Luminex assay were undetectable 14 days post infection (data not shown), and serum cytokine levels analyzed over time revealed modest induction of human cytokines including IFN-γ, TNF-α, and IL-13." (PMID 33815412, 2021). "In our study, infection of RD-A cells with the genotypes D, G and C with 1 MOI could not produce pro-inflammatory cytokines such as IFN-γ, TNF-α IL-6, IL-8, IP-10, MCP-1 as tested by Multiplex ELISA and validated by real time PCR." (PMID 34493781, 2021). "Though the difference between TNF-α expression by CD4+ T cells was not significantly different between low dose and high dose infection groups at week 3, there was a consistent increase in the TNF-α expression from pre-infection to week 3 in the high dose group." (PMID 34484203, 2021). "In addition, WT cells exhibited similar amounts of IL-1α, IL-1β, and TNF-α release with and without treatment, but lower levels of CXCL1 and IL-6 in infection supernatants." (PMID 33441602, 2021). "Though CB3-infected MDA5+/- mice have similar levels of inflammatory cytokines TNF-α, IFN-γ, IL-6, IL-17a, and IL-10 (data not shown) by day 7 following infection, CB3-infect MDA5+/- mice have greater systemic levels of both IFN-α and IFN-β compared to CB3-infected wt mice." (PMID 34804036, 2021). "At 5 h post-infection, infected or non-infected PHT, produced TNFα, IL-8 and IL-6." (PMID 34367171, 2021). "IL-1β was observed with a significant decrease in the supernatant of SFTSV infected NLRP3 KO THP-1 cells 48 h after infection compared with the wild type THP-1 cells, while no significant change of TNF-α and IL-6 was detected in the NLRP3 KO cells compared with wild type cells." (PMID 33708197, 2021).